CRABP2 (cellular retinoic acid binding protein 2)
Diseases named in the same sentence as CRABP2 in open-access papers (continued):
Sharing a sentence is not in itself a finding about the gene and the disease.
breast carcinoma (continued). "However, in ER− mammary cancer cells, the interaction of CRABP2 and Lats1 promotes the ubiquitination of Lats1 to inactivate Hippo pathway to promote the invasion and metastasis of ER− mammary cancer." (PMID 31419991, 2019). "However, how RA regulates CRABP2 in mammary cancer invasion and metastasis requires further investigation." (PMID 31419991, 2019). "We stably depleted CRABP2 in ER+ mammary cancer cells using this technique." (PMID 31419991, 2019). "However, in ER− mammary cancer cells, the interaction of CRABP2 and Lats1 promote the ubiquitination of Lats1 to inactivate Hippo pathway to promote the invasion and metastasis of ER− mammary cancer." (PMID 31419991, 2019). "Furthermore, breast cancer cells with an elevated FABP5/CRABP2 ratio show increased resistance to RA." (PMID 26142905, 2015). "The previous results show that CRABP1 and CRABP2 may have different effects on breast cancer." (PMID 31419991, 2019). "Therefore, the role of CRABP2 in regulating breast cancer invasion and metastasis and the reason that high expression of CRABP2 showed different prognosis in ER+ and ER− breast cancer remains unclear." (PMID 31419991, 2019). "In addition, CRABP2 intervenes ubiquitination of Lats1 in breast cancer cells based on ER status." (PMID 31419991, 2019). "Also, it is confirmed that CRABP2 may have different effect on invasion and metastasis in ER+ and ER− mammary cancer cells." (PMID 31419991, 2019). "The ratio of FABP5/CRABP2 was previously demonstrated to be associated with ATRA resistance in gliomas, with prognostic behavior in pancreatic ductal adenocarcinoma cell lines, with activation of PPAR instead of RAR in a breast cancer mouse model and with tumor grade and prognosis in breast cancer." (PMID 29131833, 2017). "When we applied heteroDE to breast cancer samples, we identified 7 cfRNA biomarkers (SCGB2A2, CASP14, FABP7, CRABP2, VGLL1, SERPINB5, TFF1), 3 of which (FABP7, SCGB2A2, CASP14) overlap with previously identified DCB genes." (PMID 33883548, 2021). "CRABP2 is a crucial component of the RAR pathway and can induce apoptosis in MCF-7 mammary carcinoma cells." (PMID 31962291, 2020). "In turn, RARα drives the transcription of CRABP2 except for MDA-MB-468 cells, which belongs to ER− breast cancer cells." (PMID 31419991, 2019). "We observed that knockdown of CRABP2 promotes EMT, invasion and metastasis of ER+ breast cancer cells in vitro and in vivo, whereas overexpression of CRABP2 yields the reverse results." (PMID 31419991, 2019). "Exogenous CRABP2 expression in BT549 and MDA-MB-231 cells promoted ER− breast cancer cells invasion and metastasis by monolayer wound healing and transwell assays." (PMID 31419991, 2019). "Jointly, these data show that the regulation of CRABP2 on the EMT, metastasis, and invasion depends on Lats1 in ER+ mammary cancer cells." (PMID 31419991, 2019). "In conclusion, these data indicate that the regulation of CRABP2 on the EMT, metastasis, and invasion depends on Lats1 in ER− mammary cancer cells." (PMID 31419991, 2019). "Our data indicate that CRABP1, in conjunction with previously identified CRABP2 and FABP5, plays a key role in breast cancer cell response to RA." (PMID 26142905, 2015). "In addition, several retinoic acid transport proteins have been found to correlate with increase pancreatic cancer cell motility and invasion, including CRABP2 and FABP5, while CRABP1 correlates with worse prognosis in breast cancer." (PMID 37130839, 2023). "In ER negative breast cancer cells, CRABP2 induced downregulation of Hippo pathway to promote EMT, but in ER positive breast cancer cells, CRABP2 had opposite effect on EMT." (PMID 38186580, 2023). "Therefore, knockdown of CRABP2 promotes EMT, invasion and metastasis of ER+ breast cancer cells in vitro and in vivo." (PMID 31419991, 2019). "Therefore, the ectopic expression of CRABP2 promotes EMT, invasion, and metastasis of ER− breast cancer cells in vitro and in vivo." (PMID 31419991, 2019).
breast carcinoma (continued). "That result indicated that the effect of CRABP2 on invasion and metastasis through Hippo pathway in breast cancer was independent of CRABP1." (PMID 31419991, 2019). "Also, protein and mRNA of CRABP2 was detected and found that they were significantly higher in ER+ mammary cancer cells (T47D and MCF7) than in ER− mammary cancer cells (BT549 and MDA-MB-231)." (PMID 31419991, 2019). "Our results demonstrated that CRABP2 affected the protein level and not the mRNA level of Lats1 in mammary cancer cells." (PMID 31419991, 2019). "We also screened a panel of 11 breast cancer cell lines for CRABP1 and CRABP2 expression." (PMID 26142905, 2015). "a-b Knockdown of Lats1 in ER- breast cancer cells could not modify the mRNA and protein expression of CRABP2." (PMID 31419991, 2019). "Knockdown of Lats1 in ER+ breast cancer cells could not modify the mRNA and protein expression of CRABP2." (PMID 31419991, 2019). "Additionally, acidosis-dependent changes of protein expression described for the AT1 cell line (e.g., NBC3, CRABP2) were found in our study only in the prostate carcinoma cell line but not in the Walker-256 mammary carcinoma line suggesting a cell line-specific response." (PMID 33407762, 2021). "However, the significant inhibitory effect of ATPR on the proliferation, invasion, and migration of breast cancer cells may not be directly related to the ratio of CRABP2/FABP5." (PMID 34632074, 2021). "In one study, a negative correlation was observed between CRABP2 and immune checkpoint molecules PD-1, PD-L1, and CTLA-4 across various types of tumors, including breast cancer, melanoma, gastric cancer, and testicular germ cell tumors." (PMID 39991584, 2025). "However, the FABP5/CRABP2 ratio does not always predict breast cancer cell response to RA, and RA resistance in the squamous cell carcinoma cell line COLO 16 cannot be overcome by either restoration of CRABP2 expression or an increased CRABP2/FABP5 ratio, indicating that other factors are involved." (PMID 26142905, 2015).
ovarian carcinoma (14 papers, 2016 to 2025). A malignant neoplasm originating from the surface ovarian epithelium. "Our study first investigated the role of CRABP2 in ovarian cancer prognosis and its association with chemotherapy resistance." (PMID 38195606, 2024). "Through the analysis of public databases and survival data, we found that CRABP2 mRNA was upregulated in drug-resistant ovarian cancer cells and was a significant risk factor for survival in ovarian cancer patients." (PMID 38195606, 2024). "Our study shows for the first time that CRABP2 is associated with chemotherapy resistance in ovarian cancer." (PMID 38195606, 2024). "Subsequently, we analyzed the relationship between CRABP2 and the prognosis of ovarian cancer patients using data of KmPlot, and found that CRABP2 was a significant risk factor for OS and PFS." (PMID 38195606, 2024). "Since serous ovarian cancer is the main type of ovarian cancer, we separately analyzed the relationship between CRABP2 and the prognosis of serous ovarian cancer patients, and found that CRABP2 was also a risk factor for OS and PFS in serous ovarian cancer patients." (PMID 38195606, 2024). "However, further studies are needed to fully elucidate the molecular mechanisms underlying the roles of CRABP2 and HIF1α in ovarian cancer." (PMID 38195606, 2024). "Mechanistically, we found that abnormal expression of CRABP2 can cause abnormal activity of the RA signaling pathway, leading to upregulation of HIF1α expression and increased overall metabolic activity in cells, ultimately resulting in ovarian cancer cell drug resistance." (PMID 38195606, 2024). "CRABP2 could be a promising ovarian cancer diagnostic and prognostic marker." (PMID 35578123, 2022). "In ovarian cancer, CRABP2 promotes tumorigenesis and olaparib resistance through downregulation of caspase-8 while decreasing reactive oxygen species production." (PMID 40657374, 2025). "In drug-resistant ovarian cancer cells, it was observed that CRABP2 increases HIF1α expression levels and enhances its nuclear localization." (PMID 40657374, 2025). "Then we isolated tumor cells from the ascites of eight ovarian cancer patients, and detected their sensitivity to cisplatin and CRABP2 expression levels, which showed that CRABP2 expression levels were positively correlated with the IC50 values." (PMID 38195606, 2024). "GEPIA2 data also shows that the higher the clinical stage of ovarian cancer, the higher the expression level of CRABP2 mRNA in tumor tissues." (PMID 38195606, 2024). "Multiple GSE datasets also showed that CRABP2 mRNA expression levels are significantly higher in ovarian cancer than in normal ovarian tissue." (PMID 38195606, 2024). "In conclusion, our study provides evidence that CRABP2 is closely related to the malignancy and drug resistance of ovarian cancer." (PMID 38195606, 2024). "We also conducted survival analysis in patients with different clinical stages and pathological grades, and found that regardless of early or late stage, high or low differentiation, CRABP2 was a risk factor for OS and PFS in ovarian cancer patients." (PMID 38195606, 2024). "Collectively, our results suggest that CRABP2 regulates the sensitivity of tumor cells to chemotherapy by influencing the metabolic activity of ovarian cancer cells." (PMID 38195606, 2024). "To clarify the mechanism by which CRABP2 affects the sensitivity of ovarian cancer cells to chemotherapy drugs, we conducted enrichment analysis on gene data from TCGA database." (PMID 38195606, 2024). "KmPlot’s analysis also revealed that among all ovarian cancer patients receiving chemotherapy, those with higher levels of CRABP2 expression in tumor tissue had a poorer prognosis." (PMID 38195606, 2024). "In drug-resistant ovarian cancer cells, knocking down HIF1α can block the resistance of CRABP2 to chemotherapy drugs in ovarian cancer cells." (PMID 38195606, 2024).
ovarian carcinoma (continued). "CRABP2 affects the sensitivity of ovarian cancer cells to chemotherapy drugs by increasing the overall metabolic level in these cells, and by regulating the expression of HIF1α." (PMID 38195606, 2024). "Consistent with RNA expression levels, our immunohistochemistry results demonstrated that CRABP2 protein expression was also significantly higher in ovarian cancer tissues than in corresponding normal ovarian tissues." (PMID 38195606, 2024). "In this study, we found that CRABP2 was related to the sensitivity of ovarian cancer cells to chemotherapy drugs, and the expression level of CRABP2 in drug-resistant ovarian cancer cells was significantly upregulated." (PMID 38195606, 2024). "Meanwhile, the Human Protein Atlas (HPA) detection results indicated that CRABP2 protein expression was barely detectable in normal ovarian tissues, but was expressed in ovarian cancer tissues." (PMID 38195606, 2024). "Taken together, our findings suggest for the first time that CRABP2 affects chemotherapy resistance of ovarian cancer by regulating the expression of HIF1α." (PMID 38195606, 2024). "Our results showed that HIF1α is indeed highly expressed in ovarian cancer-resistant cells, and knocking down the expression of CRABP2 led to a decrease in both HIF1 protein and RNA levels." (PMID 38195606, 2024). "One important finding of our research is that CRABP2 can affect the expression and subcellular localization of HIF1α, and the effect of CRABP2 on drug sensitivity of ovarian cancer is dependent on HIF1α." (PMID 38195606, 2024). "To better understand the role of CRABP2 in the development and progression of ovarian cancer, we compared its expression levels in normal and ovarian tissues." (PMID 38195606, 2024). "Another research showed that CRABP2 promotes the proliferation and invasion of ovarian cancer cells by upregulating the expression of EZH2." (PMID 38195606, 2024). "Immunofluorescence results in ovarian cancer cells showed that HIF1α was more prominently localized in the nucleus of resistant cells, and knocking down the expression of CRABP2 significantly reduced the level of nuclear HIF1α." (PMID 38195606, 2024). "To further analyze the relationship between CRABP2 and the prognosis of ovarian cancer patients, we used immunohistochemistry to detect the protein expression level of CRABP2 in tumor tissues from 128 patients with serous ovarian cancer." (PMID 38195606, 2024). "WAP four-disulfide core domain 2 (WFDC2/HE4) is an EOC clinical biomarker, and cellular retinoic acid-binding protein 2 (CRABP2) is upregulated in ovarian cancer and contributes to tumor growth and tumor cell migration and invasion." (PMID 37525249, 2023). "Of note, CRABP2 expression is especially higher in ovarian cancer compared to the other two genes and has a closer relationship with the survival rate of patients." (PMID 35578123, 2022). "Our data revealed an anti-tumor activity of dezocine in ovarian cancer, and identified that cellular retinoic acid binding protein 2 (CRABP2) was a downstream effector of dezocine." (PMID 36568517, 2022). "In this study, we found that CRABP2 was markedly inhibited by dezocine in ovarian cancer cells at both mRNA and protein levels by inhibiting the Akt/mTOR signaling pathway activation." (PMID 36568517, 2022). "We demonstrated three potential biomarkers—CRABP2, SPP1, and TNFAIP6, which are higher in ovarian cancer and associated with poor prognosis." (PMID 35578123, 2022). "Our data also demonstrated that CRABP2 is highly expressed in ovarian cancer cell lines and tissues (Figure A1c and d)." (PMID 36568517, 2022). "To verify the CRABP2 expression in ovarian cancer, we collected ovarian cancer tissues from patients." (PMID 35578123, 2022). "In conclusion, dezocine has significant anti-tumor effects on the growth and metastatic potential of ovarian cancer cells, and CRABP2 functions as a downstream effector of dezocine." (PMID 36568517, 2022).
ovarian carcinoma (continued). "According to receiver operating characteristic (ROC) curve analysis, CRABP2 performs better than the currently used biomarker CA125 in the diagnosis of ovarian cancer." (PMID 35578123, 2022). "We further confirmed that CRABP2 is upregulated in clinical tumor tissues of ovarian cancer patients as the malignant levels increase." (PMID 35578123, 2022). "Although some of the proteins identified in our ubiquitination dataset are known to be associated with ovarian cancer, such as CAP1, CRABP2, EPCAM or KRT8, their ubiquitination status has not been previously investigated in HGSC." (PMID 35292711, 2022). "To clarify the role and mechanism of CRABP2 in promoting tumor progression, we overexpressed CRABP2 in ovarian cancer OVCA429 cells and NM cells, and the results showed that overexpression of CRABP2 promoted cell growth." (PMID 35578123, 2022). "Transwell assay showed that the depression in cell migration induced by dezocine was significantly rescued by CRABP2 overexpression in ovarian cancer cells." (PMID 36568517, 2022). "CRABP2 is a predictive biomarker for a number of human tumors, such as ovarian cancer and non-small cell lung cancer." (PMID 33526843, 2021). "For instance, CRABP2 protein was identified as a subtype-specific biomarker of ovarian cancer, since its expression positively correlated with tumor grade and cancer stage." (PMID 32560331, 2020). "A recent study reported that ovarian cancer cell lines with a high ratio of intracellular lipid binding proteins CRABP2/FABP5, involved in retinoic acid delivery from the cytoplasm to nucleus were growth inhibited by 7 days ATRA (7 μM) treatment." (PMID 30621740, 2019). "Gene Expression Profiling Interactive Analysis 2 (GEPIA2) data showed that compared to normal tissues, the expression level of CRABP2 in various cancers is inconsistent, either upregulated or downregulated, with the highest upregulation observed in ovarian cancer." (PMID 38195606, 2024). "CRABP2 is a specific transporter of retinoic acid (RA), so we wanted to know whether RA can affect chemotherapy sensitivity of ovarian cancer cells, and whether drug sensitivity of ovarian cancer regulated by CRABP2 is related to RA." (PMID 38195606, 2024). "Further research on the molecular mechanisms involving CRABP2 could provide insights into potential therapeutic targets for ovarian cancer patients." (PMID 38195606, 2024). "Furthermore, we found that the expression levels of CRABP2 in serous ovarian cancer was higher than in other types of ovarian cancer, which was confirmed by the HPA." (PMID 38195606, 2024). "In order to analyze the molecular mechanism of CRABP2 regulating drug resistance in ovarian cancer, we conducted enrichment analysis on gene data from TCGA database, and found that CRABP2 may be involved in the metabolic regulation of ovarian cancer cells." (PMID 38195606, 2024). "In addition, we found a positive correlation between the protein expression levels of CRABP2 and HIF1α in ovarian cancer tissues, and the correlation was stronger in chemotherapy-insensitive ovarian cancer tissues." (PMID 38195606, 2024). "So, CRABP2 may play a crucial role in the development, progression, and chemotherapy resistance of ovarian cancer." (PMID 38195606, 2024). "In this study, we found that CRABP2 is highly expressed in ovarian cancer tissues and is associated with the malignancy of the tumor and the prognosis of ovarian cancer patients, and that CRABP2 expression level is related to the sensitivity of ovarian cancer cells to chemotherapy drugs." (PMID 38195606, 2024). "Additionally, CRABP2 was found to be highly expressed in ovarian cancer tissues compared to normal tissues, and its expression level correlated positively with tumor malignancy, including histopathological grade, clinical stage, and metastasis." (PMID 38195606, 2024).